KIAA0040 (KIAA0040)
Synonyms: IAMP
Tractability: Antibody: UniProt predicts a signal peptide or a membrane-spanning region.
Gene: Protein-coding gene on chromosome 1 (175,156,986 to 175,193,265, reverse strand). Ensembl gene ENSG00000235750.
Subcellular location: Membrane
Subcellular location (Human Protein Atlas): Nucleoplasm
Gene Ontology:
Cellular component: membrane
Genetic constraint (gnomAD): Loss-of-function variants: 10 observed, 7.68 expected, observed/expected ratio (o/e) 1.3, 90% interval 0.79 to 1.88. That is too few expected variants to judge how well the gene tolerates losing a copy. Missense variants: 86 observed, 111.91 expected, observed/expected ratio (o/e) 0.77, 90% interval 0.64 to 0.92. Synonymous variants: 47 observed, 41.27 expected, observed/expected ratio (o/e) 1.14, 90% interval 0.9 to 1.45.
Homologues: Orthologues: chimpanzee KIAA0040 (99% identical), macaque KIAA0040 (98% identical), dog KIAA0040 (84% identical), pig KIAA0040 (81% identical), guinea pig KIAA0040 (79% identical), rat Kiaa0040 (76% identical), mouse 4930523C07Rik (71% identical), tropical clawed frog KIAA0040 (51% identical).
Diseases named in the same sentence as KIAA0040 in open-access papers:
KIAA0040 is named in the same sentence as 19 diseases in open-access papers, as found by Europe PMC text mining. Sharing a sentence is not in itself a finding about the gene and the disease. The quoted sentences say what the papers report.
alcohol dependence (2 papers, 2012 to 2013). Physical and psychological dependence on alcohol. "A meta-analysis using data from these sources also found the KIAA0040 gene significantly associated with alcohol dependence." (PMID 24829844, 2013). "A recent genome-wide association study using SAGE (the Study of Addiction: Genetics and Environment) and COGA (Collaborative Study on the Genetics of Alcoholism) found five SNPs within the KIAA0040 gene significantly associated with alcohol dependence." (PMID 24829844, 2013). "The SNP showing the most significant association with alcohol dependence affected status was rs1008459 (FBAT p = 0.006) located within intron 2 of KIAA0040." (PMID 24829844, 2013). "Based on the FBAT within-family association analyses, our results suggest that variation in the KIAA0040 gene is associated with risk for alcohol dependence in families with multiple cases of alcohol dependence." (PMID 24829844, 2013). "Family-based association analysis shows the KIAA0040 gene significantly associated with alcohol dependence." (PMID 24829844, 2013). "Two nearby genes, KIAA0040 and TNN have been mapped to 1q25.1 and have been recently identified in genome-wide association analyses as being significantly related to alcohol dependence." (PMID 24829844, 2013). "However, KIAA0040 has shown genome-wide significance for alcohol dependence in a large case/control data set." (PMID 24829844, 2013). "However, in spite of this limitation we observed a significant relationship between SNPs within the KIAA0040 gene and alcohol dependence suggesting that this gene may have clinical importance in the etiology of alcohol dependence." (PMID 24829844, 2013). "The KIAA0040 gene is flanked by two genes TNN and TNR with a plausible role in alcohol dependence." (PMID 24829844, 2013).
dependence (2 papers, 2012 to 2013). "One two SNP block (Block 5) which consisted of one SNP within the KIAA0040 gene (rs2272785) and an adjacent SNP (rs3753555) showed an association with affected status with a p value of 0.041 using a broader SUD phenotype and 0.034 when restricted to alcohol abuse or dependence only." (PMID 24829844, 2013).
brain tumours (1 paper, 2024). "The IFS of Ki‐67 was performed on the brain tumours, elucidating that KIAA0040 knockdown suppressed Ki‐67 expression in comparison to the control group." (PMID 38661644, 2024). "The IFS of Ki‐67 in the brain tumours depicted that KIAA0040 overexpression resulted in larger tumour size and increased Ki‐67 expression in comparison to the control group." (PMID 38661644, 2024).
breast carcinoma (1 paper, 2010). "The role of KIAA0040 in cancer progression is also supported by a recent study where KIAA0040 overexpression was shown to correlate with poor prognosis in breast cancer." (PMID 20822536, 2010).
colorectal cancer (1 paper, 2013). A primary or metastatic malignant neoplasm that affects the colon or rectum. "There is evidence that the KIAA0040 protein product may represent one of the tumor antigens expressed on colorectal cancer cells and recognized by tumor reactive T-cells (CT28 line)." (PMID 24829844, 2013).
glioma (1 paper, 2024). A benign or malignant brain and spinal cord tumor that arises from glial cells (astrocytes, oligodendrocytes, ependymal cells). "Our study found that KIAA0040 was increased in glioma and linked to tumour grade and poor clinical outcomes, serving as an independent prognostic factor." (PMID 38661644, 2024). "The association between KIAA0040 overexpression and the cascade of glioma progression indicates its potential as a key contributor to glioma development and aggressive behaviour." (PMID 38661644, 2024). "The molecular mechanisms underlying the role of KIAA0040 in gliomas still require further investigation." (PMID 38661644, 2024). "Our study shows that overexpression of KIAA0040 is linked to glioma malignancy through the JAK2/STAT3 pathway." (PMID 38661644, 2024). "Consistently, we demonstrate that KIAA0040 overexpression promotes glioma cell migration and invasion, which is possibly mediated via the JAK2/STAT3 pathway activation." (PMID 38661644, 2024). "Here, we examined the effects of KIAA0040 knockdown in glioma cells utilising shRNAs targeting KIAA0040 in A172 and LN229 cells." (PMID 38661644, 2024). "A gene pathway enrichment analysis was conducted to elucidate the molecular mechanism by which KIAA0040 promotes glioma cell proliferation and invasion." (PMID 38661644, 2024). "The RT‐PCR analysis was performed to investigate further the expression of KIAA0040 in different grades of human gliomas." (PMID 38661644, 2024). "In this study, KIAA0040 expression levels were evaluated using qRT‐PCR, WB and IHC, and functional assays were conducted to assess its impact on glioma progression, along with animal experiments." (PMID 38661644, 2024). "Of course, we also verified the expression abundance of KIAA0040 in various cell subpopulations in low‐grade and high‐grade glioma single cell cohorts." (PMID 38661644, 2024). "This research suggests a new treatment strategy for gliomas, but more studies are needed to confirm these results and investigate targeting the KIAA0040‐JAK/STAT3 axis for therapy." (PMID 38661644, 2024). "Functional assays, including the CCK8, colony formation, and transwell assays, were conducted to assess the impact of KIAA0040 knockdown on the proliferation and invasion potential of glioma cells." (PMID 38661644, 2024). "The results found that higher KIAA0040 expression was correlated with older age and higher glioma grade." (PMID 38661644, 2024). "Although the role of KIAA0040 in glioma cell lines was established, its role in vivo remained unclear." (PMID 38661644, 2024). "Of course, KIAA0040 enhances glioma growth by preventing tumour cell death and promoting cell cycle advancement." (PMID 38661644, 2024). "The results manifested that silencing KIAA0040 significantly impeded glioma cell proliferation and invasion." (PMID 38661644, 2024). "By demonstrating the influence of KIAA0040 overexpression on glioma cell proliferation and invasion, we offer evidence for the strong tumorigenicity of KIAA0040 in gliomas." (PMID 38661644, 2024). "Altogether, our results indicate that KIAA0040 promotes glioma cell migration and invasion through the JAK2/STAT3 pathway activation." (PMID 38661644, 2024). "The IHC analysis results showed that the immune SI of KIAA0040 was significantly different among different glioma grades." (PMID 38661644, 2024). "The analysis results demonstrated that KIAA0040 was overexpressed in glioma tissues compared to NBTs." (PMID 38661644, 2024). "The CCK8 assay, which measures cell viability and proliferation, depicted that KIAA0040 overexpression significantly enhanced glioma cell proliferation." (PMID 38661644, 2024). "This highlights the potential of KIAA0040 as a therapeutic glioma target and emphasizes the need for further research to elucidate its precise molecular mechanisms and explore its therapeutic implications." (PMID 38661644, 2024).
glioma (continued). "Functional assays showed that KIAA0040 enhances glioma growth, migration and invasion by activating the JAK2/STAT3 pathway." (PMID 38661644, 2024). "This indicates that KIAA0040 is crucial in promoting glioma cell proliferation and invasion." (PMID 38661644, 2024). "Furthermore, the results of the transwell assay revealed that KIAA0040 overexpression significantly raised glioma cell invasion and migration." (PMID 38661644, 2024). "This study investigated the oncogenic role of KIAA0040 in glioma progression." (PMID 38661644, 2024). "Our findings suggest that targeting KIAA0040 could be an effective treatment for glioma due to its role in promoting aggressive tumour behaviour and poor prognosis." (PMID 38661644, 2024). "This implies the potential role of KIAA0040 as a prognostic marker in gliomas." (PMID 38661644, 2024). "Moreover, there was a correlation between higher glioma grades and overexpressed KIAA0040 at the RNA and protein levels." (PMID 38661644, 2024). "Moreover, we conducted various assays to assess the impact of KIAA0040 on the potential of glioma cells to proliferate and invade." (PMID 38661644, 2024). "This indicates that KIAA0040 may promote the glioma cell invasive behaviour, a characteristic feature of malignant tumours." (PMID 38661644, 2024). "The results proposed that KIAA0040 is crucial in driving glioma malignant progression." (PMID 38661644, 2024). "Besides, the flow cytometric study results demonstrated that KIAA0040 knockdown promotes glioma cell apoptosis and halts the cell cycle progression." (PMID 38661644, 2024). "The WB results indicated that glioma tissues had higher KIAA0040 expression than NBTs." (PMID 38661644, 2024). "In addition, we also verified the correlation between KIAA0040 and immune cell infiltration abundance in low‐grade and high‐grade gliomas." (PMID 38661644, 2024). "The results showed that KIAA0040 expression varied across different grades of gliomas." (PMID 38661644, 2024). "Similarly, the colony formation assay, which evaluates the ability of cells to form colonies, demonstrated that KIAA0040 overexpression enhanced the colony formation capacity of glioma cells." (PMID 38661644, 2024). "The role of KIAA0040 role in glioma development is not yet understood despite its connection to nervous system diseases." (PMID 38661644, 2024). "Previous studies have not connected KIAA0040 to glioma progression." (PMID 38661644, 2024).
Insulin resistance (1 paper, 2019). Increased resistance towards insulin, that is, diminished effectiveness of insulin in reducing blood glucose levels. "Prostate androgen-regulated mucin-like protein 1 (PARM1), ALDH4A1, VENTX, and KIAA0040 are novel biomarkers for the development of insulin resistance." (PMID 30678306, 2019).
cancer (4 papers, 2010 to 2025). A tumor composed of atypical neoplastic, often pleomorphic cells that invade other tissues. "Next, we used the TCGA database to conduct a related pan‐cancer analysis of KIAA0040, the results show that KIAA0040 is highly expressed in most tumour tissues." (PMID 38661644, 2024). "Notably, seven UReg genes (GALNT14, KIAA0040, EPB41L1, ZNF469, BLNK, AK7, and WSCD1) are associated with the progression of various cancers in humans." (PMID 40241800, 2025). "In the iC3 subtype, which was associated with the most aggressive SKCM cases, FAM135B gene mutation frequencies were increased, while CD8A, GBP5, KIAA0040, and SAMHD1 expression were downregulated, suggesting that these genes play important roles in cancer development and immune responses." (PMID 32639949, 2020).
tumor (3 papers, 2013 to 2025). "Our study examined KIAA0040 expression in several cell lines to investigate its role in tumour cells." (PMID 38661644, 2024). "Our findings revealed that KIAA0040 overexpression was significantly related to larger tumour size and poorer survival outcomes." (PMID 38661644, 2024).
KIAA0040 also shares sentences with these, for which no sentence is quoted: migraine (2 papers); alcohol abuse (1); Alcoholism (1); cardiac diseases (1); cocaine dependence (1); leukemia (1); major depressive disorder (1); nervous system diseases (1); Obesity (1); opiate dependence (1).